LAMA2 (laminin subunit alpha 2)
Diseases named in the same sentence as LAMA2 in open-access papers (continued):
Sharing a sentence is not in itself a finding about the gene and the disease.
Sepsis (3 papers, 2013 to 2023). Sepsis is defined as life-threatening organ dysfunction caused by a dysregulated host response to infection. "In the present study, mutations in ENTPD1, ZFAND4, DNAH11 and LAMA2 increased the risk of comorbid sepsis in severely burned patients." (PMID 36659877, 2023). "At the genetic level, seven susceptibility genes for sepsis in severe burn patients were found: DNAH11, LAMA2, ABCA2, ZFAND4, CEP290, MUC20 and ENTPD1." (PMID 36659877, 2023). "Through genomic analysis, we identified seven important susceptibility genes (DNAH11, LAMA2, ABCA2, ZFAND4, CEP290, MUC20 and ENTPD1) in patients with severe burn injuries complicated with sepsis." (PMID 36659877, 2023). "The DNAH11, ZFAND4, LAMA2 and ENTPD1 genes have been shown to have protective effects against sepsis." (PMID 36659877, 2023).
Arrhythmia (2 papers, 2021 to 2024). Any cardiac rhythm other than the normal sinus rhythm. "This relationship may provide valuable insights into how LAMA2 mutations contribute to arrhythmia conditions, emphasizing the need for cardiac monitoring in patients with these mutations." (PMID 38398418, 2024).
COVID-19 (2 papers, 2023). A disease caused by infection with severe acute respiratory syndrome coronavirus 2. "The most changed components of BM included laminins (LAMB2, LAMA2, LAMC3, LAMB1, LAMC1, and LAMA5) and proteoglycans (COL18A1, HSPG2, and AGRN), with some BM specific collagens (IV, VIII, XVIII, and V collagens) remaining in COVID-19 brains, as compared with the control brains." (PMID 36609561, 2023).
diabetes (2 papers, 2021 to 2022). "Another switch gene, LAMA2, is a serum protein biomarker for pre-diabetes and is implicated in high-fat diet-induced obesity." (PMID 36389068, 2022). "Several switch genes, including AKT3, LAMA2, ADCY1, RAB3A, RAPGEF4, and ABCC8, have been implicated in insulin signaling and diabetes." (PMID 36389068, 2022). "As a consequence, we found that patients with pre-diabetes had a 4 fold higher serum LAMA2 level than healthy subjects." (PMID 33995275, 2021). "After immunoblotting analysis of healthy patients as well as patients with pre-diabetes and brain stroke, LAMA2, MLL4, and PLXDC2 emerged as potential (pre-)diabetic markers." (PMID 33995275, 2021). "First, LAMA2, MLL4 and PLXDC2 are novel diagnostic markers for pre-diabetes." (PMID 33995275, 2021). "In our study, LAMA2 level in pre-diabetic patients was higher than in healthy subjects, implying that LAMA2 could be a promising marker in (pre-)diabetes and its complications." (PMID 33995275, 2021). "LAMA2, MLL4 and PLXDC2 may be suitable diagnostic markers for (pre-)diabetes." (PMID 33995275, 2021). "Additionally, comparison of the expression level of LAMA2, MLL4, PLXDC2, CD14, CLU, CD99 and SAA2 in sera of healthy volunteers and patients with stroke and pre-diabetes suggests that LAMA2, MLL4 and PLXDC2 have better specificity for (pre-)diabetes than CD14, CLU, CD99 and SAA2." (PMID 33995275, 2021). "Moreover, LAMA2, MLL4 and PLXDC2 may be worth investigating for diabetes development." (PMID 33995275, 2021).
Hypertension (2 papers, 2007 to 2023). The presence of chronic increased pressure in the systemic arterial system. "Association with hypertension was identified at α = 0.05 significance level at rs2244008 (A/G) and rs2272996(C/T) in the LAMA2 and VNN1 genes, respectively." (PMID 18043751, 2007). "The likely pathogenic variations in CDH6, SRFBP1 and LAMA2 may assist in disorganization of the ECM components and cytoskeleton, leading to hypertension." (PMID 36833422, 2023).
Obesity (2 papers, 2021 to 2022). Accumulation of substantial excess body fat. "While interesting and deserving of further investigation in mice, there appears to be no obvious association at present between LAMA2 and obesity in humans." (PMID 34394003, 2021).
pancreatic cancer (2 papers, 2023 to 2025). "ANGPTL4 may play a role in creating a feedback loop that supports pancreatic cancer progression, while the down-regulation of the ECM protein LAMA2 is likely associated with pancreatic cancer advancement." (PMID 39811640, 2025). "In summary, Lama2 expression in fibroblasts is decreased in both human and murine pancreatic cancer models." (PMID 39811640, 2025). "LAMA2, an extracellular matrix gene with reduced expression, suppressed pancreatic cancer cell migration, proliferation, and invasion." (PMID 39811640, 2025). "To further explore the functional effects of LAMA2, we used recombinant LAMA2 in murine pancreatic cancer cells (KPC3595)." (PMID 39811640, 2025). "LAMA2 has also been found well correlated with tumor sites and to predict poor survival in pancreatic cancer." (PMID 37238942, 2023).
pituitary adenoma (2 papers, 2019 to 2023). "In pituitary adenoma, the methylation alteration of LAMA2, GALNT9 and DAP methylation has been proven to be related to tumor invasion." (PMID 31796052, 2019).
sarcoglycanopathies (2 papers, 2020 to 2024). "Animal models for sarcoglycanopathies and LAMA2-RD exist, and they adequately mirror the disease course in humans." (PMID 38926599, 2024).
sarcoma (2 papers, 2020 to 2022). A usually aggressive malignant neoplasm of the soft tissue or bone. "Although MDN1, HMCN1 and LAMA2 mutation were universally present and significantly different among the three groups, up until now there was no study had reported the mutation of these three genes in any kind of sarcoma." (PMID 36153483, 2022).
anaplastic ependymoma (1 paper, 2016). Anaplastic ependymoma is a rare, malignant type of ependymoma that most often arises in the supratentorial region of the brain of children and young adults and that manifests with variable symptoms including headaches, nausea, vision impairment, memory loss and difficulty walking. "TNC positive tumors were more frequently anaplastic ependymomas, whereas this association could not be found for LAMA2 positive tumors." (PMID 27550150, 2016).
astrocytoma (1 paper, 2025). "To determine whether vessel-adjacent T cells reside in the perivascular space, we stained 15 IDHmt astrocytoma samples containing high T cell quantities for CD3, CD31, and Laminin-α2 (LAMA2; a marker for the parenchymal basement membrane)." (PMID 39880824, 2025).
autoimmune disease (1 paper, 2024). A disorder resulting from loss of function or tissue destruction of an organ or multiple organs, arising from humoral or cellular immune responses of the individual to their own tissue constituents. "Nevertheless, LAMA2 is hypo-methylated and over-expressed in fibroblast-like synoviocytes of RA patients compared to patients affected by other arthritic or autoimmune diseases." (PMID 38803542, 2024).
autosomal recessive limb-girdle muscular dystrophy (1 paper, 2024). Autosomal recessive form of limb-girdle muscular dystrophy. "Another example is autosomal recessive limb-girdle muscular dystrophy, which is caused by mutations in laminin-α2 (LAMA2) or its receptor α-dystroglycan (DAG1)." (PMID 38197427, 2024).
Brain atrophy (1 paper, 2022). Partial or complete wasting (loss) of brain tissue that was once present. "Patients with LAMA2-RDs characteristically exhibit white matter brain changes by magnetic resonance imaging (MRI), with some exhibiting brain atrophy and neuronal migration defects, with symptoms often including seizures." (PMID 35639486, 2022).
chronic lymphocytic leukemia (1 paper, 2025). "ASNP rs2306029, in LAMA2 (Laminin Subunit Alpha 2), has been reported to increase the substantial risk for Richter syndrome, a rare transformation of chronic lymphocytic leukemia to an aggressive type." (PMID 41300981, 2025).
Cockayne syndrome (1 paper, 2025). A multisystem condition characterized by short stature, a characteristic facial appearance, premature aging, photosensitivity, progressive neurological dysfunction, and intellectual deficit. "LSDs were the most common GLEs reported in our work (25.6%), followed by Cockayne syndrome (20.9%) and LAMA2-related CMD (12.8%)." (PMID 40514726, 2025).
colitis (1 paper, 2021). Inflammation of the colon. "Forty-eight genes with SNP/InDel mutation were overlapped in the three colitis tissues, two (Wnt3a and Lama2) of which are in the cancer development-related signaling pathway." (PMID 34764977, 2021).
demyelinating peripheral neuropathies (1 paper, 2017). "Loss-of-function mutations in LAMA2 causes Congenital Muscular Dystrophy 1A, which include demyelinating peripheral neuropathies characterized by heterogeneous myelin thickness with focal hypermyelination, loss of nerve fibers, short internodes, and wide nodes of Ranvier." (PMID 28636612, 2017).
demyelination (1 paper, 2017). "In the CNS, Lama2 is expressed by PCs and upregulated during OPC differentiation (14 dpl) in a toxin-induced demyelination model." (PMID 28834740, 2017).
eosinophilia (1 paper, 2024). "For example, muscle eosinophilia in the dyW mouse model of LAMA2-CMD correlates with increased eotaxin expression in the skeletal muscle in dyW mice, although eotaxin levels in the serum of dyW mice are normal." (PMID 38340007, 2024).
glaucoma (1 paper, 2023). Increased pressure in the eyeball due to obstruction of the outflow of aqueous humor. "Rare, deleterious SNVs in AQP5, SRFBP1, CDH6 and FOXM1 from POAG families and in ACACB, RGL3 and LAMA2 from PACG families were found exclusively in glaucoma cases." (PMID 36833422, 2023). "Prioritized gene variants in our glaucoma case-control cohort supported possible causal roles in four genes for POAG (AQP5, FOXM1, SRFBP1 and CDH6) and three genes in PACG (LAMA2, ACACB and RGL3)." (PMID 36833422, 2023).
Hyperglycemia (1 paper, 2023). An increased concentration of glucose in the blood. "The laminins LAMA2 and LAMB4 are targets in the treatment of ocriplasmin vitreomacular adhesion, whereas the amylases AMY2A and MGAM are targeted by acarbose, voglibose and miglitol for the improvement of postprandial hyperglycemia." (PMID 37684227, 2023).
hyperthyroidism (1 paper, 2023). Overactivity of the thyroid gland resulting in overproduction of thyroid hormone and increased metabolic rate. "The corresponding mutated genes set that has common effects on hyperthyroidism in children included IGF1, CACNA1S, MYH7, IL6, TTN, CACNB2, LAMA2, and DMD." (PMID 37876543, 2023).
hypertrophic cardiomyopathy (1 paper, 2023). A condition in which the myocardium is hypertrophied without an obvious cause. "“Hypertrophic cardiomyopathy” in the signal pathway was followed with the p.adjust value of 1.10×10-3 and the corresponding collective action gene set with mutations included 8 genes: IGF1, CACNA1S, MYH7, IL6, TTN, CACNB2, LAMA2, DMD." (PMID 37876543, 2023).
Hypoglycemia (1 paper, 2020). A decreased concentration of glucose in the blood. "Ten patients with CMD (5 with LAMA2-related muscular dystrophy) reported at least one episode of hypoglycemia beginning at an average age of 3.5 years." (PMID 32028919, 2020).
kidney stone (1 paper, 2025). "Plasma metabolites (Mannose and Threonate) are key mediators in the diet–kidney stone nexus, and the downregulation of LAMA2 and CSNK1G3 is associated with a decreased risk of kidney stones, providing insights into potential therapeutic targets." (PMID 40842671, 2025). "Consistently, previous studies have reported that the downregulation of genes like LAMA2 in CaOx stone patients suggests that alterations in extracellular matrix interactions and signaling pathways may contribute to kidney stone formation." (PMID 40842671, 2025). "Furthermore, our pathway enrichment analysis demonstrated that LAMA2 and CSNK1G3 were linked to Mannose/Threonate and kidney stone formation through shared pathways, including the PI3K‐Akt signaling pathway, ECM–receptor interaction, and Focal adhesion." (PMID 40842671, 2025). "Moreover, our analysis indicated that LAMA2 and CSNK1G3 are key genes that are downregulated in kidney stones." (PMID 40842671, 2025).
leiomyoma (1 paper, 2025). A well-circumscribed benign smooth muscle neoplasm characterized by the presence of spindle cells with cigar-shaped nuclei, interlacing fascicles, and a whorled pattern. "DEX-treatment reduced LAMA2 and increased CNN1 levels (coding for extracellular matrix and smooth muscle proteins, respectively) in FKBP5-silenced vs scramble siRNA-transfected leiomyoma cultures." (PMID 40290045, 2025).
leprosy (1 paper, 2022). Leprosy is a chronic infectious disease affecting primarily the skin and peripheral nervous system. "Our LAMA2-based peptide targeting PGL-1 might have the potential tospecifically block this key molecule, suggesting that the preferentialregion of the peptide is involved in the initial contact during theattachment of leprosy bacilli to Schwann cells." (PMID 35857971, 2022).
liver cancer (1 paper, 2014). An epithelial or non-epithelial malignant neoplasm that arises from the liver. "Interestingly, we observed frequent mutations in the extracellular matrix gene LAMA2 in liver cancer patients." (PMID 25159915, 2014). "The non-focal nature of LAMA2 mutations in liver cancer suggests it plays a tumor suppressor role." (PMID 25159915, 2014).
liver steatosis (1 paper, 2024). "However, the other liver steatosis gene markers, such as Thbs2, Lum, Lamc3, Lama2, Akr1b10, Col4a4, A2m, and C7, were not significantly different between the db-HF and db-HC groups." (PMID 38613031, 2024).
low grade glioma (1 paper, 2025). A grade I or grade II glioma arising from the central nervous system. "Other relevant pathways in cancer, such as focal adhesion, cytoskeleton regulation, and chemokine signalling (VCL, THBS1-4, FLNA, LAMA2/4/5, HSPG2), might also be influenced indirectly by changes in the WWOX/HIF1A ratio, potentially impacting the overall prognosis of low-grade glioma patients." (PMID 41007296, 2025).
meningioma (1 paper, 2023). A generally slow growing tumor attached to the dura mater. "Specifically, NF2 meningiomas expressed higher levels of arachnoid CLDN11 and pial LAMA2, while TRAF7 tumors overexpressed dural MGP and dural/arachnoid CRABP2 relative to NF2 tumors." (PMID 36937440, 2023).
migraine (1 paper, 2023). "It should be noted that patient 5 had variants in one migraine gene, SLC35D2, and two inner ear genes, OTOP1 and LAMA2." (PMID 37107589, 2023). "The resulting subnetwork included 9 genes: migraine-associated genes APOE, LRP1, CARF, CTIF, RNF213, and ECM1; LAMA2, which is associated with vestibular anomalies in mice; and the neurodevelopment-associated genes MYO5A and KLC2." (PMID 37107589, 2023).
posterior fossa ependymoma (1 paper, 2016). A high grade ependymoma that is located within the posterior fossa. "Together with miRNA analysis, we conducted expression studies of LAMA2 and NELL2 genes, which have been suggested as a possible prognostic factors for children with posterior fossa ependymomas." (PMID 27390862, 2016).
prediabetes (1 paper, 2025). "LAMA2 deficiency is associated with impaired skeletal muscle metabolism, where muscle IR is a major driver of prediabetes." (PMID 40162315, 2025). "Using this technique, researchers identified LAMA2, MLL4, and PLXDC2 as novel serum biomarkers for prediabetes, with 0-20% higher specificity and 20-40% greater sensitivity than FBG and HbA1c." (PMID 40162315, 2025).
prostate adenocarcinoma (1 paper, 2017). "It is noteworthy that two LAMA2 variants p.R2578* and p.I136M were detected in cases with both colon and prostate adenocarcinomas." (PMID 29212164, 2017).
refractive error (1 paper, 2022). A defect in the focusing of light on the retina as in astigmatism, myopia, or hyperopia. "LAMA2 variant rs12193446 is associated with refractive error early in life and then progressively through childhood, consistent with children’s duration of exposure to education." (PMID 36395078, 2022).
renal hypertension (1 paper, 2016). Hypertension caused by the kidney's hormonal response to narrowing or occlusion of the renal arteries. "Seven of them (Agtr1a, Fn1, Gja1, Lama2, Mmp2, Mmp9, Nos3) are known as being associated with renal hypertension." (PMID 28105926, 2016). "The changes in expression of DEGs associated with renal hypertension (Agtr1a, Fn1, Gja1, Lama2, Mmp2, Mmp9, Nos3) may also be suggested to have a significant impact on disease development in ISIAH rats." (PMID 28105926, 2016).
respiratory infection (1 paper, 2021). "In total, 58.9% (63/107) of LAMA2-CMD and 35.7% (5/14) of LGMDR23 patients had a history of recurrent respiratory infection, mainly at ages of 0–3 years and 6–15 years." (PMID 34281576, 2021).
restless legs syndrome (1 paper, 2017). A condition that occurs while resting or lying in bed; it is characterized by an irresistible urgency to move the legs to obtain relief from a strange and uncomfortable sensation in the legs. "LAMA2 also regulates other genes, such as the ladybird homeobox corepressor 1 (LBXCOR1), which is a corepressor of transcription playing a role in GABAergic phenotype of interneurons in some areas of the brain, associated for instance to the susceptibility to restless legs syndrome." (PMID 28279172, 2017).
situs inversus (1 paper, 2026). A congenital condition in which there is complete right-to-left reversal of the position of the major thoracic and abdominal organs (that is, they are arranged in a mirror image of the normal positioning). "In this case, genetic testing identified likely pathogenic variants in LAMA2 and NDUFAF5, neither of which is associated with laterality defects, suggesting the patient's situs inversus is likely idiopathic." (PMID 41788120, 2026).
status epilepticus (1 paper, 2021). Status epilepticus is defined as a continuous seizure lasting more than 30 min, or two or more seizures without full recovery of consciousness between any of them. "In addition, two LAMA2-CMD patients died of status epilepticus." (PMID 34281576, 2021).
Stroke (1 paper, 2021). Sudden impairment of blood flow to a part of the brain due to occlusion or rupture of an artery to the brain. "LAMA2, MLL4 and PLXDC2 are specifically expressed in (pre-)diabetic sera; CD99 is expressed in the sera of both healthy and (pre-)diabetic patients; and CD14, CLU and SAA2 are expressed in the sera of healthy, (pre-)diabetic and stroke subjects." (PMID 33995275, 2021).
systemic amyloidosis (1 paper, 2021). "For example, screening for systemic amyloidosis in patients with gelsolin mutation, as well as cardiac and respiratory disease in patients with mutations in MYH7, DMD and LAMA2 genes." (PMID 34103343, 2021).
toxoplasmosis (1 paper, 2018). A parasitic disease contracted by the ingestion or fetal transmission of toxoplasma gondii. "The toxoplasmosis pathway encompasses JAK-STAT signalling as well as extra-cellular matrix interactions and laminins (LAMA2 and LAMC3)." (PMID 29447208, 2018).
Vertigo (1 paper, 2023). An abnormal sensation of spinning while the body is actually stationary. "Two other genes, HMX3 and LAMA2, were identified to have rare missense variants in children with vertigo and are strongly expressed in human vestibular tissues." (PMID 37107589, 2023).